UNC5CL (unc-5 family C-terminal like)
Description:
Inhibits NF-kappa-B-dependent transcription by impairing NF-kappa-B binding to its targets.
Synonyms: ZUD; MGC34763; MUXA
Tractability: Antibody: UniProt predicts a signal peptide or a membrane-spanning region.
Gene: Protein-coding gene on chromosome 6 (41,026,895 to 41,039,221, reverse strand). Ensembl gene ENSG00000124602.
Subcellular location: Membrane; Cytoplasm
Subcellular location (Human Protein Atlas): Cytosol; Centrosome
Gene Ontology:
Molecular function: peptidase activity; protein binding; netrin receptor activity
Biological process: positive regulation of canonical NF-kappaB signal transduction; positive regulation of JNK cascade; netrin-activated signaling pathway; signal transduction
Cellular component: cytosol; membrane; plasma membrane; cytoplasm
Genetic constraint (gnomAD): Loss-of-function variants: 42 observed, 55.28 expected, observed/expected ratio (o/e) 0.76, 90% interval 0.59 to 0.98. The upper end of that interval is the gene's LOEUF score, 0.98, which puts it in group 4 of 6, group 1 being the genes least tolerant of losing a copy. Missense variants: 619 observed, 695.82 expected, observed/expected ratio (o/e) 0.89, 90% interval 0.83 to 0.95. Synonymous variants: 285 observed, 296.84 expected, observed/expected ratio (o/e) 0.96, 90% interval 0.87 to 1.06.
Homologues: Orthologues: chimpanzee UNC5CL (99% identical), macaque UNC5CL (96% identical), dog UNC5CL (89% identical), pig UNC5CL (89% identical), rabbit UNC5CL (89% identical), guinea pig UNC5CL (84% identical), mouse Unc5cl (84% identical), rat Unc5cl (82% identical), Caenorhabditis elegans unc-5 (18% identical), Drosophila melanogaster unc-5 (16% identical). Paralogues in human: UNC5B (26% identical), UNC5C (25% identical), UNC5D (24% identical), UNC5A (24% identical).
Diseases named in the same sentence as UNC5CL in open-access papers:
UNC5CL is named in the same sentence as 5 diseases in open-access papers, as found by Europe PMC text mining. Sharing a sentence is not in itself a finding about the gene and the disease. The quoted sentences say what the papers report.
cancer (2 papers, 2019 to 2021). A tumor composed of atypical neoplastic, often pleomorphic cells that invade other tissues. "Restricted cell cycle genes in interferon-inducible pathways include antiviral and anti-cancer activity (Ifit1 and Ifit2) and pro-inflammatory reactions recruiting immune cells to target cells (genes Stat1 and Unc5cl)." (PMID 34202278, 2021). "Interestingly, three out of the five non-synonymous mutated genes, Transmembrane Channel Like 3 (TMC3), Olfactory Receptor Family 6 Subfamily K Member 6 (OR6K6), and Unc-5 Family C-Terminal Like (UNC5CL), have been reported on in regard to an involvement with various cancer types." (PMID 31842489, 2019).
tumour (2 papers, 2017 to 2021). "The following marker genes were differentially expressed in the triphasic tumours relative to the blastemal tumours: PA (LHX1), RV/CSB/SSB (BMP2, CDH6, JAG1, PAPSS2), ePT and/or imHL (CIDEB, CLIC6, UNC5CL, VDR), and early DT/imHL (KCNJ1)." (PMID 29040332, 2017).
UNC5CL also shares sentences with these, for which no sentence is quoted: dementia (1 paper); neurodegenerative disease (1); oral squamous cell carcinomas (1).